RNU6-1240P (RNA, U6 small nuclear 1240, pseudogene)
Gene: Small nuclear RNA gene on chromosome 1 (186,311,825 to 186,311,928, reverse strand). Ensembl gene ENSG00000202025.
Homologues: Orthologues: chimpanzee U6 (100% identical), macaque U6 (83% identical), guinea pig U6 (77% identical), pig U6 (67% identical). Paralogues in human: RNU6-509P (85% identical), RNU6-536P (85% identical), RNU6-1083P (84% identical), RNU6-562P (84% identical), RNU6-820P (84% identical), RNU6-1152P (83% identical), RNU6-1243P (83% identical), RNU6-19P (83% identical), RNU6-35P (83% identical), RNU6-45P (83% identical), RNU6-543P (83% identical), RNU6-1019P (82% identical), and 1287 more.